HSPA4 (heat shock protein family A (Hsp70) member 4)
Diseases named in the same sentence as HSPA4 in open-access papers (continued):
Sharing a sentence is not in itself a finding about the gene and the disease.
tumor (continued). "Understanding the functions of HSPA4 not only offers profound insights into its roles in tumor progression but may also pave the way for innovative therapeutic strategies and targets in the future." (PMID 38305786, 2024). "In a model of spontaneous lymph node metastasis of breast cancer, these unique B cells accumulated in tumor-draining lymph nodes and produced a large amount of pathologic IgG immunoglobulin, which activated the NF-κB pathway by binding to the tumor cell surface HSPA4 protein." (PMID 37215990, 2023). "Indeed, it has been suggested that tumor growth was associated with accumulation of regulatory B cells (Breg) within TDLNs, which in turn could promote cancer cells recruitment via the production of anti-HSPA4 immunoglobulin and the activation of the CXCL12/CXCR4 pathway." (PMID 38074683, 2023). "Therefore, we assumed that HSPA4 increased the treatment sensitivity by promoting cell-cycle transitions of tumor cells, resulting in superior response to nCRT in the TR group with higher HSPA4 levels." (PMID 35292026, 2022). "HSPA4 and HSPA14 expressions were significantly associated with various tumor grades." (PMID 34059060, 2021). "HSPA4 expression can accurately identify tumor from normal tissue (AUC = 0.957)." (PMID 34754620, 2021). "Besides, the high HSPA1A, HSPA1B, HSPA4, HSPA5, HSPA8, HSPA13, and HSPA14 expressions were inversely associated with the overall survival rate of patients, tumor grade, and cancer stage." (PMID 34059060, 2021). "Tumor-bearing mice had higher serum IgG levels, which could bind glycosylated HSPA4 proteins." (PMID 37419983, 2023). "Similarly, HSPA4, HSPA8, HSPA9, and HSPA12B are associated with tumor occurrence and development." (PMID 34059060, 2021). "The research found that the LINC01004/hsa-miR-125b-2-3p/HSPA4 axis inhibits ferroptosis in HCC cells by affecting GPX4 activity and iron metabolism, thereby influencing tumor progression." (PMID 40386780, 2025). "By coculturing tumor cells with CD8+ T cells, we demonstrate that HSPA4 upregulation suppresses the cytotoxicity of CD8+ T cells." (PMID 38589927, 2024). "When tumor cells with high expression of HSPA4 are treated with PD1 blockade therapy, CD8+ T cells are re-activated and cell toxicity is restored, then tumor cells respond better to PD1 checkpoint blockade therapy." (PMID 38589927, 2024). "HSPA4 overexpression upregulates ALKBH5 via increasing its protein stability, leading to decrease of CD58 of tumor cells and increase of PD1/PDL1 axis, finally to impair the toxicity of CD8+ T cells and immune evasion of GC cells." (PMID 38589927, 2024). "Similar to the mRNA levels, HSPA4, PANX1, and HSP90AA1 were significantly elevated in LUAD tumor tissues compared to normal tissues." (PMID 37259066, 2023). "Expectedly, HSPA4 overexpression increased the levels of HSPA4, HSPA5, CHOP, SDC-1, SDCBP-1, SOX4, FZD4, and β-catenin in tumor tissues, but 4-PBA inhibited the generation of these proteins." (PMID 35442158, 2022). "In summary, our results indicate that HSPH1, HSPD1, SERPINH1, HSPA4, and HSP90AA1 are significantly upregulated in HNSC patients and their upregulation is negatively correlated with HNSC tumor stage." (PMID 32523426, 2020). "We also analyzed HSPH1, HSPD1, SERPINH1, HSPA4, and HSP90AA1 expression as a function of the HNSC tumor stage." (PMID 32523426, 2020). "The results revealed that HSPA4 expression was higher in tumor tissues than matched non-tumor tissues (P < 0.05)." (PMID 38589927, 2024). "HSPA4, SPTB and NIPSNAP1 in tumor biopsies and/or their optional combinations might be potential predictive markers for nCRT response in patients with LARC." (PMID 35292026, 2022). "These are preliminary results based on a small cohort, however, the results suggest that the tumor tissue-derived proteins (HSPA4, SPTB and NIPSNAP1) and a combination of HSPA4 and SPTB, could achieve relatively high predictive ability for nCRT sensitivity." (PMID 35292026, 2022).
tumor (continued). "HSPA4 belongs to the HSP110 family and is related to tumor progression and outcomes." (PMID 35292026, 2022). "In addition, HSPA4 overexpression activated ER stress and Syntenin/SOX4/Wnt/β-catenin pathway in TNBC cells, and also stimulated TNBC tumor growth in 4-PBA-treated mice." (PMID 35442158, 2022). "HSPA4, a member of Heat Shock Protein family (HSP), which act as molecular chaperones in conditions of stress and tumorigenesis, suppresses apoptosis and enhances the aggressiveness and prognosis of tumor tissue." (PMID 33395399, 2021). "Therefore, the high HSPA4 and HSPA14 expressions are associated with tumor proliferation, invasion and metastasis, indicating that their high expressions could influence the prognosis of HCC patients by accelerating tumor proliferation, invasion, and metastasis of tumor." (PMID 34059060, 2021). "HSPA4, also known as HSP70RY, is a member of the HSP70 chaperone family proposed to rescue premature degradation of pVHL mutants, inducing their stabilization and halting tumor progression." (PMID 30943211, 2019). "The differential interactome composition indicates a functional shift in EGFR signaling that may drive increased tumor cell adhesion (CD44, ITGB1, FN1), metabolic adaptation (GAPDH, ENO1) and stress response (HSPA4, HSP90AB1), consistent with mechanisms observed in therapy‐resistant CRC phenotypes." (PMID 41319168, 2025). "Secondly, we unveil a novel mechanism of immune evasion of GC cells: HSPA4 overexpression in GC cells decreases CD58 via ALKBH5/CD58 pathway, activates PD1/PDL1 axis, decreases cytotoxicity and infiltration of CD8+ T cells and induces tumor immunosuppressive microenvironment." (PMID 38589927, 2024). "However, the tumor weight and volume in mice with 4-PBA were increased after HSPA4 overexpression." (PMID 35442158, 2022). "We compared the protein levels of HSPA4, ALKBH5 and CD58 in tumor tissues between responders and non-responders by using mfIHC." (PMID 38589927, 2024). "Increased HSPA4 (P < 0.01), ALKBH5 (P < 0.05) and decreased CD58 (P < 0.05) were observed in tumor tissues of responders compared with non-responders." (PMID 38589927, 2024).
cancer (29 papers, 2014 to 2025). A tumor composed of atypical neoplastic, often pleomorphic cells that invade other tissues. "To evaluate the diagnostic significance of HSPA4 across a spectrum of cancers, we employed the ROC curve analysis." (PMID 38305786, 2024). "Our findings illuminate the intrinsic association between HSPA4 expression and the diagnosis and prognosis of various cancers, underscoring its potential clinical relevance." (PMID 38305786, 2024). "Given the paramount diagnostic and predictive prowess HSPA4 showcases as a cancer biomarker, it’s evident that while its high expression commonly suggests an unfavorable outcome, exceptions like KIRC do exist." (PMID 38305786, 2024). "In summation, HSPA4 displays widespread elevated expression in a vast majority of cancers, notably those associated with the digestive system." (PMID 38305786, 2024). "The research findings reveal significant differences in HSPA4 expression across different cancer types, suggesting its diagnostic value and close association with cancer staging and patient survival rates." (PMID 38305786, 2024). "Collectively, augmented expression of HSPA4 is generally linked with an adverse cancer prognosis, especially pronounced in cancers like ESAD, LIHC, and LUAD." (PMID 38305786, 2024). "In the meantime, these B cells selectively promoted cancer cell lymph node metastasis by producing pathogenic IgG that targeted the glycosylated membrane protein HSPA4 of cancer cells." (PMID 32746880, 2020). "Furthermore, our ROC analysis demonstrated a noteworthy diagnostic value of HSPA4 across various cancers, with its AUC frequently surpassing the 0.7 mark, strongly indicating its potential as a bio-marker for oncology." (PMID 38305786, 2024). "Collectively, our insights into the genetic variations and methylation patterns of HSPA4 across different cancers provide a novel perspective on its functional role in oncology, laying the groundwork for potential targeted therapeutic strategies in the future." (PMID 38305786, 2024). "To delve deeper into the molecular mechanisms of tumorigenesis, we employed a myriad of bioinformatics approaches to investigate the role of HSPA4 in various cancers, aiming to assess its potential value in clinical diagnosis and prognosis." (PMID 38305786, 2024). "Compared to normal tissue counterparts, we observed elevated methylation levels of HSPA4 in cancer types, including LIHC, CHOL, THCA, HNSC, KIRP, LUSC, and BRCA." (PMID 38305786, 2024). "A deeper understanding of HSPA4 not only unveils its central function in oncology but also offers potential avenues for cancer treatment, especially in refining immunotherapeutic strategies." (PMID 38305786, 2024). "In cancers where HSPA4 expression significantly impacts prognosis, four genes—HSP90AA1, HSPA8, DNAJB1, and HSP90AB1—demonstrated a pronounced correlation." (PMID 38305786, 2024). "In conclusion, the genetic variations and methylation patterns of HSPA4 across various cancers furnish novel insights, potentially expounding its function and role in oncology." (PMID 38305786, 2024). "Delving deeper into the CPTAC dataset, a pronounced correlation was discerned between HSPA4 expression and the pathological staging of cancer." (PMID 38305786, 2024). "Exploring the application of HSPA4 inhibitors or vaccines in cancer therapy is another important research direction." (PMID 38305786, 2024). "HSPA4 (heat shock protein family A (Hsp70) member 4), a representative of the Hsp110 family, is upregulated in various cancer types." (PMID 38589927, 2024). "We further stratified the cancer patients into high and low HSPA4 expression groups and utilized the TCGA dataset to investigate the association between HSPA4 expression and patient prognosis." (PMID 38305786, 2024). "Employing univariate Cox regression analysis, we scrutinized the association between HSPA4 expression and OS, DSS, and PFI across different cancer types." (PMID 38305786, 2024).
cancer (continued). "In our heatmap analysis focused on HSPA4 expression with respect to immune cells, a significant correlation between B cells, T cells, and various cancers emerged, suggesting their integral role in the oncogenic progression modulated by HSPA4." (PMID 38305786, 2024). "Understanding how HSPA4 interacts with other proteins and signaling pathways, and how these interactions impact cancer development and treatment, are also crucial." (PMID 38305786, 2024). "While current research primarily focuses on the role of HSPA4 in specific cancers, its universal function across cancer types remains a relatively uncharted domain." (PMID 38305786, 2024). "In essence, these observations accentuate the potential central role of HSPA4 in modulating immune responses and influencing cancer progression." (PMID 38305786, 2024). "Recently, HSPA4 has come under the spotlight due to its potential oncogenic role across various cancers." (PMID 38305786, 2024). "Future studies should emphasize conducting more clinical research to verify the role of HSPA4 in human cancers and its potential as a therapeutic target." (PMID 38305786, 2024). "Furthering our investigation, we assessed the expression patterns of HSPA4 within immune subtypes across seven distinct cancers." (PMID 38305786, 2024). "In summary, HSPA4 emerges as a promising cancer biomarker and a vital member of the HSPs family, holding potential applications in diagnosis, prognosis, and immunotherapy." (PMID 38305786, 2024). "Across various cancer types, the HSPA4 gene emerges as a pivotal player, underscoring its central role in tumorigenesis and cancer progression." (PMID 38305786, 2024). "Delving deep into the TIMER2.0 tool, TCGA, GTEx, and CPTAC databases, we found marked variability in HSPA4 expression across multiple cancers." (PMID 38305786, 2024). "In the majority of cancers, an elevated expression of HSPA4 was concomitant with a diminished survival rate." (PMID 38305786, 2024). "These novel findings furnish invaluable insights into the role of HSPA4 in the landscape of cancer single-cell studies." (PMID 38305786, 2024). "Strikingly, in KIRC, an extraordinary amplification of HSPA4 mRNA was observed, potentially playing a critical regulatory role in cancer progression." (PMID 38305786, 2024). "Our results highlighted marked discrepancies in HSPA4 expression amongst subtypes in cancers including KIRC (spanning 6 subtypes), ESCA (5 subtypes), COAD (5 subtypes), STAD (5 subtypes), READ (5 subtypes), LUAD (5 subtypes), and LIHC (5 subtypes)." (PMID 38305786, 2024). "Addressing this gap, we embarked on the first comprehensive investigation of HSPA4 across cancers, aiming to elucidate its broader biological significance." (PMID 38305786, 2024). "Collectively, heightened HSPA4 expression implies diminished survival rates in a majority of cancer types." (PMID 38305786, 2024). "Using Kaplan-Meier survival plots combined with univariate Cox regression analysis, we assessed the prognostic relevance of HSPA4 in diverse cancers." (PMID 38305786, 2024). "From an analysis spanning 30 distinct cancer types, we detected a prevalent shallow deletion in HSPA4 mRNA across the majority of tumors." (PMID 38305786, 2024). "Contrarily, in COAD and READ cancers, a significant reduction in HSPA4 promoter methylation was discerned." (PMID 38305786, 2024). "In most cancer cells, HSPA4 is expressed abundantly to play a protective role but induces the intense ER stress." (PMID 35442158, 2022). "Overexpression of HSPA4 considerably correlated with cancer stage and alpha-fetoprotein (AFP) level in HCC." (PMID 34754620, 2021). "To explore the possible roles of HSPA4, we first analyzed its expression in 26 types of human cancer." (PMID 34754620, 2021). "It has previously been demonstrated that HspA4 has a stabilising effect on VEGFA mRNA in cancer cells." (PMID 34222357, 2021).
cancer (continued). "R package was used to analyze the correlation between HSPA4 and cancer stage, and to establish receiver operating characteristic (ROC) curve of diagnosis, time-dependent survival ROC curve, and a nomogram model." (PMID 34754620, 2021). "A statistically significant relationship was found between HSP90AA1 and HSPA4 overexpression and poor overall survival in cancer patients, as it is indicated by pooled hazard ratio (HR) values greater than 1 and p values less than 0.05." (PMID 31814876, 2019). "IPA analysis of these unique up-regulated genes indicated that some genes were associated with cell transformation during cancer progression (ABL1, TRIO, FOSB, NRCAM, TRIB2 and CDK6) and others with cell survival (e.g., BCL10, BBC3, FGF8, HSPA4 and SOD1)." (PMID 29137349, 2017). "In summary, we have conducted a comprehensive pan-cancer analysis of HSPA4 for the first time." (PMID 38305786, 2024). "Accumulating evidences showed that HSPA4 might not only participate in the progression but also immune regulation in some cancers." (PMID 38589927, 2024). "Advanced research on HSPA4 not only holds the promise to elucidate its precise function in oncology but might also herald innovative avenues for future cancer therapeutic endeavors, particularly enhancing the efficacy of immunotherapeutic strategies." (PMID 38305786, 2024). "Moreover, the methylation status of the HSPA4 promoter region and its implications for diverse cancers remained central to people’s inquiries." (PMID 38305786, 2024). "Furthermore, analysis from CPTAC revealed a correlation between HSPA4 expression and the pathological staging of cancers such as KICH, KIRP, BLCA, KIRC, LUAD, and LIHC, suggesting a potential influence of HSPA4 on the staging of these malignancies." (PMID 38305786, 2024). "We posit that HSPA4 stands as a robust biomarker for cancer, with applications in diagnosis and prognostic prediction, and may also emerge as a potential molecular target for future therapies." (PMID 38305786, 2024). "Hence, elucidating the methylation patterns of HSPA4 in cancers is pivotal for understanding its role in tumorigenesis and progression." (PMID 38305786, 2024). "In summary, despite certain progress, many unknown areas in HSPA4 research remain to be explored further, to better harness this protein’s potential in cancer therapy." (PMID 38305786, 2024). "Given the complexity of cancer, HSPA4 may play varying roles in different cancer types, necessitating further research for deeper exploration." (PMID 38305786, 2024). "Across a broad spectrum of cancers, we assessed the expression levels of HSPA4 using TIMER2.0." (PMID 38305786, 2024). "This study employs various bioinformatics techniques to delve into the role of HSPA4 in pan-cancer." (PMID 38305786, 2024). "Based on these findings, there is reason to propose that HSPA4 could serve as a promising biomarker for the diagnosis and prognosis of various types of cancer, and as a potential target for immunotherapy." (PMID 38305786, 2024). "The role of HSPA4 was shown both for cancer and neurodegenerative diseases." (PMID 37298337, 2023). "In this study, we found that HSPA4 was significantly unregulated in most of the human cancers." (PMID 34754620, 2021). "Higher HSPA4 expression showed a worse prognosis and a more advanced cancer stage." (PMID 34754620, 2021). "Patients who were in a more advanced cancer stage tended to express a higher level of HSPA4." (PMID 34754620, 2021). "In addition, it has been previously reported that HSPA4 and HSPA8 were associated with poor prognosis in cancer." (PMID 32971786, 2020). "In addition, the prognostic potential of HSP90AA1 and HSPA4 overexpression for cancer patients' overall survival was investigated." (PMID 31814876, 2019). "Thus, a pan-cancer, in-depth study of HSPA4 is of paramount importance." (PMID 38305786, 2024).